UCHL1 (ubiquitin C-terminal hydrolase L1)
Diseases named in the same sentence as UCHL1 in open-access papers (continued):
Sharing a sentence is not in itself a finding about the gene and the disease.
plasmacytoma (2 papers, 2015 to 2021). Plasmacytoma is a localized mass of neoplastic monoclonal plasma cells that represents approximately 5% of all plasma cell neoplasms. "In mouse model, UCHL1 was found to be crucial for the development of B-cell lineage, which shows as plasmacytoma histology." (PMID 34257568, 2021).
prostate tumor (2 papers, 2011 to 2012). "Methylation specific PCR and pyrosequencing results demonstrated that UCHL1 suppression in primary prostate tumour tissues is linked to its promoter DNA methylation." (PMID 21999842, 2011).
renal carcinoma (2 papers, 2024). A carcinoma arising from the epithelium of the renal parenchyma or the renal pelvis. "However, it is important to not overlook the negative correlation between UCHL1 expression and other biological processes, such as the insulin-like growth factor receptor signaling pathway, as it has been reported to play a role in renal cancer tumorigenesis." (PMID 39034372, 2024).
small cell lung carcinoma (2 papers, 2021 to 2023). Small cell lung cancer (SCLC) is a highly aggressive malignant neoplasm, accounting for 10-15% of lung cancer cases, characterized byrapid growth, and early metastasis. "Analog 34 displayed anti-migratory properties in SW1271 small cell lung cancer cell lines consistent with observed behavior from genetic depletion of UCHL1." (PMID 33668938, 2021). "The resulting UbV (UbVT9F/T66K) served as a UCHL1-selective UbV-ABP, but it unexpectedly displayed preferential binding for UCHL3 over UCHL1 when used in small cell lung cancer cell lysates." (PMID 37626927, 2023).
uterine serous carcinoma (2 papers, 2024 to 2026). "The treatment of ARK1 xenograft uterine serous carcinoma mice with the UCHL1 inhibitor LDN-57444 reduced tumor growth." (PMID 38727276, 2024). "Additionally, in uterine serous carcinoma, UCHL1 interacts with cyclin B1, which is essential for mitosis during tumor cell cycle progression." (PMID 38727276, 2024).
abortion (1 paper, 2024). the ending of pregnancy by removing a fetus or embryo before it can survive outside the uterus. "Collectively, these results indicated that UCHL1 was downregulated in the decidua from abortion patients, and the defect of UCHL1 was associated with the impaired decidualization and aberrant modulation of dNKs." (PMID 38769534, 2024). "By extension, the expression of UCHL1 was also decreased in the decidua from abortion patients (abortion decidua), as indicated by IHC staining and immunofluorescence of UCHL1." (PMID 38769534, 2024). "Then, we examined whether the UCHL1 inhibition-induced abortion symptoms were due to decidualization failure." (PMID 38769534, 2024). "Furthermore, inhibition of UCHL1 in normal DSCs recapitulated the phenotype of abortion DSCs, underscoring the pivotal role played by UCHL1 in maintaining dNK modulation by DSCs." (PMID 38769534, 2024). "To evaluate whether UCHL1 regulates the recruitment and education of dNKs by DSCs, we initially examined the expression profile of chemokines and cytokines in DSCs derived from normal pregnancy or abortion patients." (PMID 38769534, 2024). "Nevertheless, when pretreated with LDN57444, an inhibitor of UCHL1, the expression of CXCL12, IL15 and TGF-β in normal DSCs was significantly decreased, as well as their ability to recruit and educate dNKs, which were similar to that of the abortion DSCs." (PMID 38769534, 2024).
alcoholic liver diseases (1 paper, 2024). A disorder caused by damage to the liver parenchyma due to alcohol consumption. "A reduced UCHL1 activity is related to increased BACE1 and Aβ peptide accumulation in the brain; UCHL1 was found to be upregulated in hepatic stellate cells upon activation in fibrosis, as well as in samples from patients with alcoholic liver disease." (PMID 39201455, 2024).
aneurysm (1 paper, 2021). Bulging or ballooning in an area of an artery secondary to arterial wall weakening. "Through literature searches we found that the participant of ubiquitination related proteins (e.g. UCHL1, RNF213, UBR3, ARIH1) in pathogenesis of above-mentioned human aneurysm subtypes (ASH, AAA, CA, AA, AD) has been widely reported before." (PMID 34895131, 2021).
asthma (1 paper, 2022). "We studied expression of innervation markers: ubiquitin carboxy-terminal hydrolase L1 (UCHL1/PGP9.5) and occludin (OCLN) as well as genes reported to be associated with asthma: periostin (POSTN), galectin-3 (LGAL3), secretory leukocyte protease inhibitor (SLPI), IL-4, IL-5, IL-13, IL-17." (PMID 35534846, 2022).
autosomal recessive spastic paraplegia (1 paper, 2020). "Mutations in UCHL1 have been described in three families with autosomal recessive spastic paraplegia (SPG79)." (PMID 32656641, 2020).
behavioural disorders (1 paper, 2015). "Although UCHL1 was previously reported to be expressed in neurons, testis and ovary, we did not observe any obvious side effects after the administration of LDN57444, such as reductions in body weights or behavioural disorders, at least in our experimental setting." (PMID 25615526, 2015).
Behr syndrome (1 paper, 2020). A disorder characterized by early-onset optic atrophy along with neurological features, including ataxia, spasticity, and intellectual disability. "The detection of UCHL1 mutations in this phenotype adds another molecular mechanism, protein de-ubiquitination contributing to Behr syndrome and raising the possibility that this gene is also contributing to mitochondrial protein quality control." (PMID 32656641, 2020).
cataract (1 paper, 2011). Partial or complete opacity of the crystalline lens of one or both eyes that decreases visual acuity and eventually results in blindness. "However, the associations found were quite weak and argue against any pivotal role for the UCHL1 p.S18Y polymorphism in cataract disease." (PMID 21268678, 2011).
cholangiocarcinoma (1 paper, 2015). A carcinoma that arises from the intrahepatic biliary tree (intrahepatic cholangiocarcinoma) or from the junction, or adjacent to the junction, of the right and left hepatic ducts (hilar cholangiocarcinoma). "Either up-regulation or down-regulation of UCHL1 has been observed in cholangiocarcinoma." (PMID 25971332, 2015). "In addition, UCHL1 expression was more frequently observed in patients with regional lymph node metastasis, implicating UCHL1 acting as a cholangiocarcinoma oncogene." (PMID 25971332, 2015).
chronic hepatitis B (1 paper, 2017). "The paraffin-embedded liver sections from patients with CHC (n = 5) and chronic hepatitis B (CHB, n = 5) were obtained and were analyzed by immunochemitry staining using anti-UCHL1 antibody to understand whether UCHL1 is specifically present in patients with CHC." (PMID 28667290, 2017).
clear cell renal cell carcinoma (1 paper, 2024). "This study explored the protein expression levels of UCHL1, SNRNP200, and PAK4 in clear cell renal cell carcinoma (CCRCC) using advanced proteomic techniques." (PMID 39199615, 2024).
dependence (1 paper, 2025). "The identification of clinically validated biomarkers (GFAP, UCHL1, CHI3L1) in the dependence group suggests potential for developing diagnostic and monitoring tools for alcohol-related brain injury." (PMID 41292811, 2025).
endometrial tumors (1 paper, 2020). "When analysing all endometrial tumors in the TCGA data set, a positive correlation with aneuploidy score was observed for both UCHL1 RNA expression and cyclin B1 protein levels." (PMID 31906456, 2020). "UCHL1 RNA and protein expression was undetectable in cell lines derived from type I endometrial tumors except for MFE-280 and MFE-296, but detected in all type II cell lines except ACI-158." (PMID 31906456, 2020).
gad (1 paper, 2007). "For example, the genetic defect in a mouse model of gracile axonal dystrophy (gad) was shown to be caused by an in-frame deletion that includes exons 7 and 8 of Uchl1, encoding UCHL1." (PMID 18047736, 2007).
head injuries (1 paper, 2022). "In 2018, the Food and Drug Administration (FDA) permitted the marketing of a panel of two biomarkers, glial fibrillary acidic protein (GFAP) and ubiquitin C-terminal hydrolase-L1 (UCH-L1), as a screening test for intracranial abnormalities in adults with head injuries presenting to the ED setting." (PMID 36484020, 2022).
hypertrophic cardiomyopathy (1 paper, 2020). A condition in which the myocardium is hypertrophied without an obvious cause. "Nonetheless, the presentation in these cases raises the possibility that hypertrophic cardiomyopathy may be an additional feature of the clinical syndrome associated with UCHL1 mutations." (PMID 32656641, 2020). "Further studies will be required to ascertain how the c.627_629del; p.(Gly210del) UCHL1 mutation might lead to clinical hypertrophic cardiomyopathy." (PMID 32656641, 2020).
Infertility (1 paper, 2023). "UCHL1 is associated with endometrial development, and its deletion leads to infertility." (PMID 37797697, 2023).
Intellectual disability (1 paper, 2023). "The two associations with an MOI that was unsupported in the literature were between UCHL1 and dominant ‘Inherited optic neuropathies’ and between SLC39A8 and dominant ‘Intellectual disability’." (PMID 36928819, 2023).
internal carotid artery stenosis (1 paper, 2019). Carotid stenosis is a narrowing or constriction of the inner surface (lumen) of the carotid artery, usually caused by atherosclerosis. "However, these observed changes in serum CNDP1 and UCHL1 concentrations do not necessarily warrant a change in recommendations concerning the use of CEA in patients with high-grade internal carotid artery stenosis." (PMID 31460820, 2019).
intervertebral disc degeneration (1 paper, 2025). "Further mechanistic studies have revealed that UCHL1 regulates HSPA8 through deubiquitination, thereby activating the chaperone-mediated autophagy pathway, which plays a critical protective role in delaying intervertebral disc degeneration." (PMID 41346614, 2025).
invasive ductal carcinomas (1 paper, 2017). "Also, UCHL1 expression in invasive ductal carcinomas significantly correlated with the triple negative phenotype." (PMID 28589855, 2017).
lentivirus infection (1 paper, 2023). Virus diseases caused by the Lentivirus genus. "Considering the certain broad spectrum of lentivirus infection, we further constructed the adeno-associated viruses (AAV) with the advantages of lower immunogenicity and tissue-specific infection to specifically overexpress UCHL1 in NSCs in vivo." (PMID 37507386, 2023).
liver cirrhosis (1 paper, 2018). "Higher UCHL1 expression was correlated with liver cirrhosis and presence of microvascular invasion." (PMID 29846044, 2018).
liver disease (1 paper, 2024). "In this model, exposure of liver slices to the well-characterised autocrine stimulators of fibrosis, TGFβ1+ PDGFβ, robustly induces fibrogenesis, thus, pharmacological inhibition of UCHL1/HIF signalling in this model is highly relevant for translation to human liver disease." (PMID 38808772, 2024). "As we also show that UCHL1 inhibition blunts fibrogenesis in a pre-clinical 3D human liver slice model of fibrosis, these results demonstrate how small molecule inhibitors of DUBs can exert therapeutic effects through modulation of HIF transcription factors in liver disease." (PMID 38808772, 2024).
lung diseases (1 paper, 2023). "Although higher epithelial expression of UCHL1 has been reported in smokers, the underlying molecular mechanism is not fully understood, and a role for UCHL1 in the pathogenesis of lung diseases remains to be determined." (PMID 38016026, 2023). "Since cigarette smoking is a major cause of lung diseases, we studied its effect on UCHL1 expression and DNA methylation patterns in human bronchial epithelial cells, obtained after laser capture micro-dissection (LCM) or isolated from residual tracheal/main stem bronchial tissue." (PMID 38016026, 2023). "We explored the possible role of UCHL1 in smoking-related lung diseases via chemical inhibitor treatment and conventional plasmid-based upregulation in cell lines." (PMID 38016026, 2023).
metabolic syndrome (1 paper, 2025). A cluster of metabolic risk factors for CARDIOVASCULAR DISEASES and TYPE 2 DIABETES MELLITUS. "Ubiquitin C-terminal hydrolase L1 (UCH-L1) is a protein in the ubiquitin–proteasome system involved in numerous cellular processes and implicated in various human diseases, including cancer, neurodegenerative diseases, and metabolic syndrome." (PMID 40825585, 2025).
Miscarriage (1 paper, 2024). A pregnancy that ends at a stage in which the fetus is incapable of surviving on its own, defined as the spontaneous loss of a fetus before the 22th week of pregnancy. "In conclusion, our findings demonstrated that UCHL1 deficiency was a critical cause of miscarriage, which was due to aberrant decidualization and impaired dNK modulation." (PMID 38769534, 2024). "All these discoveries indicate that UCHL1 is a crucial regulator in pregnancy, and its defects contribute to miscarriage." (PMID 38769534, 2024). "The Ubiquitin C-terminal hydrolase L1 (UCHL1), as a deubiquitinating enzyme, was significantly downregulated in decidua from patients with miscarriage, along with impaired decidualization and decreased dNKs." (PMID 38769534, 2024). "In human samples, we observed downregulation of UCHL1 in DSCs isolated from the decidua of miscarriage patients, accompanied by impaired decidualization." (PMID 38769534, 2024). "Its deficiency indicates a poor pregnancy outcome due to defective decidualization, making UCHL1 a potential target for the diagnosis and treatment of miscarriage." (PMID 38769534, 2024). "Overall, these findings demonstrated that UCHL1 inhibition resulted in miscarriage, which was attributed to decidualization failure along with defects in dNK modulation as well as enhancement of inflammation." (PMID 38769534, 2024). "Pharmacological inhibition of UCHL1 in pregnant mice resulted in severe symptoms of miscarriage, firmly confirming its protective role in pregnancy." (PMID 38769534, 2024). "Our findings provide evidence that UCHL1 is critical for decidualization as well as the recruitment and education of dNKs and therefore represents a potential target for the diagnosis and treatment of miscarriage." (PMID 38769534, 2024). "To further investigate the roles of UCHL1 in miscarriage related to aberrant decidualization, we treated pregnant mice with corn oil containing DMSO or LDN57444 from GD5 to 7 when murine ESCs undergo decidualization, and on GD8, the pregnancy outcome was observed." (PMID 38769534, 2024). "Therefore, we explored whether UCHL1 blockage-induced miscarriage was due to impaired decidualization." (PMID 38769534, 2024). "Moreover, we verified that UCHL1 played an important role in maintaining successful decidualization and pregnancy in mice, suggesting a conserved function of UCHL1 in pregnancy, which made it feasible to test the efficacy of medicine targeting UCHL1 on miscarriage in a mouse model." (PMID 38769534, 2024). "A recent finding reveals that within the uterus during early pregnancy of mice, UCHL1 is specifically expressed in decidual cells; however, the roles of UCHL1 have not been explored in miscarriage related to impaired decidualization." (PMID 38769534, 2024). "In the present study, we found that UCHL1, a deubiquitinating enzyme that regulates ubiquitinating and deubiquitinating dynamics, was significantly decreased in decidual tissue obtained from patients with miscarriage, highlighting the critical role of UCHL1 in maintaining normal pregnancy." (PMID 38769534, 2024).
mood disorder (1 paper, 2025). A cognitive disorder a disturbance in which the person's mood is hypothesized to be the main underlying feature. "Clinically, this supports the utility of biomarker profiling for risk stratification, early intervention, and personalized therapeutic strategies, such as targeted modulation of SUMOylation or UCHL1 activity, to enhance neuroresilience and mitigate progression to severe mood disorders." (PMID 41155506, 2025).
morbid obesity (1 paper, 2019). An excess of body weight, normally defined as an individual with a body mass index greater than 35 or a body weight greater than one hundred percent of ideal body weight. "Fortunately, another study proposed that both short- and long-term weight loss could lead to downregulation of UCHL1, which supports UCHL1 as a target for morbid obesity treatment." (PMID 31929791, 2019).
neuroblastic tumor (1 paper, 2018). A group of nervous system tumors which display neuronal differentiation. "However, patients with high expression of UCHL1 in the TMA cohort of neuroblastic tumors held significantly good OS." (PMID 30359286, 2018).
olfactory neuroblastoma (1 paper, 2022). An olfactory neuroblastoma arising in the paranasal sinus. "This predicts UCHL1 and KRT18 to be a potentially valuable marker combination for the differentiation of olfactory neuroblastomas and the SNUC classes." (PMID 36443295, 2022).
Pc (1 paper, 2024). "Closer examination suggested that OGN+/UCHL1+ cell abnormalities in proliferation and migration lead to abnormal Pc formation in hairless pigs and that BMP and TGFβ are the first signaling pathways that trigger OGN+/UCHL1+ cells to undergo Pc formation." (PMID 38561967, 2024).
radiation pneumonitis (1 paper, 2023). Inflammation of the lung due to harmful effects of ionizing or non-ionizing radiation. "In addition, EC UCHL1 has also been reported to attenuate the activity of TNF-α, an inflammatory cytokine that has itself been implicated as a key mediator of radiation pneumonitis." (PMID 37830619, 2023).
relapsing (1 paper, 2023). "Our current study showed, that besides leptin and fibronectin, also plasma UCHL1 could be a promising high-sensitive potential biomarker of relapsing–remitting MS, as it was the most useful in differentiating RRMS patients from healthy individuals." (PMID 36854961, 2023).
scrapie (1 paper, 2014). A fatal disease of the nervous system in sheep and goats, characterized by pruritus, debility, and locomotor incoordination. "The observed downregulation of PSMA7 and UCHL1 may facilitate prion conversion, implicating these genes in the pathogenic mechanism of the scrapie." (PMID 24450868, 2014). "The downregulation of PSMA7 and UCHL1 genes and the positive association of PrPSc deposition with PSMB8 expression in both preclinical and clinical stages of natural scrapie in the LRS of sheep is in line with the impaired proteasome function described in prion diseases of the nervous system." (PMID 24450868, 2014). "Genes encoding proteins involved in molecular pathways that regulate protein misfolding (PSMA7, UCHL1 and PFDN2) were downregulated in scrapie-infected animals." (PMID 24450868, 2014).
uterine corpus endometrial carcinoma (1 paper, 2021). A endometrial carcinoma (disease) that involves the body of uterus. "As shown, colonic adenocarcinoma (COAD), uterine corpus endometrial carcinoma (UCEC), kidney renal papillary cell carcinoma (KIRP) and kidney renal clear cell carcinoma (KIRC) patients with high UCHL1 levels had a poor prognosis." (PMID 34016791, 2021).